ALMS1 (ALMS1 centrosome and basal body associated protein)
Diseases named in the same sentence as ALMS1 in open-access papers (continued):
Sharing a sentence is not in itself a finding about the gene and the disease.
cardiomyopathy (18 papers, 2009 to 2026). A disease of the heart muscle or myocardium proper. "This is in contrast to the suggestion that the sexually dimorphic cardiomyopathy in female Alms1 KO mice is purely metabolically mediated and, instead, indicates that cardiomyocyte-autonomous Alms1 deficiency plays an important and, perhaps, dominant role." (PMID 38756069, 2024). "One clue was offered by identification of biallelic ALMS1 mutations in four infants who either died or underwent heart transplantation because of mitogenic cardiomyopathy, defined by persistent postnatal mitogenesis of cardiomyocytes." (PMID 38756069, 2024). "This is in keeping with the mitogenic cardiomyopathy described in four infants with biallelic ALMS1 loss-of-function mutations." (PMID 38756069, 2024). "In conclusion, only female Alms1-deficient adult mice show echocardiographic evidence of cardiac dysfunction, consistent with the cardiomyopathy of AS." (PMID 38756069, 2024). "Altogether, our findings indicate that ALMS1, which is expressed in neonatal heart, has been associated with cardiomyopathy, as the candidate causal gene in pEFE phenotype." (PMID 34387706, 2021). "Together, in agreement with other reported cases of AS-associated mitogenic cardiomyopathy, the novel ALMS1 variant abolished ALMS1 protein expression and localization at the centrioles and delayed cardiomyocyte proliferation arrest in pEFE heart." (PMID 34387706, 2021). "Since the Ki67 antibody has been used to assess cardiomyocyte nuclear proliferative activity in mitogenic cardiomyopathy, it was used to assess the nuclear activity in the Sphynx cats with the ALMS1 variants and hypertrophic cardiomyopathy reported here." (PMID 33639992, 2021). "Since ALMS1 is the only gene in which recessive mutations are known to cause AS manifestations, including cardiomyopathy, we ascertained the inheritance pattern, leading to appropriate counseling." (PMID 34387706, 2021). "Recent evidence suggests that the ALMS1 protein has a role in perinatal cardiomyocyte cell division and replication, and that its deficiency can cause mitogenic cardiomyopathy." (PMID 32503575, 2020). "Previously we and others reported mutations in the ALMS1 gene as a cause of mitogenic cardiomyopathy." (PMID 29357359, 2018). "This patient had a milder phenotype than other patients with convincing biallelic ALMS1 mutations, and also reported two siblings with cardiomyopathy, blindness and deafness." (PMID 28717663, 2017). "Confirmation of significant mutations in the ALMS1 gene should lead to advice to screen the subject for cardiomyopathy, and metabolic disorders." (PMID 19515241, 2009). "The heart failure was thus attributed to ALMS1-associated cardiomyopathy." (PMID 39596324, 2024). "Secondarily we reviewed published mutations in ALMS1 with cardiomyopathies in the literature." (PMID 36109815, 2022). "This study demonstrates a novel form of cardiomyopathy associated with ALMS1 in the cat." (PMID 33639992, 2021). "Thus, several patients with ALMS1 mutations show mitogenic cardiomyopathy, a rare form of dilated cardiomyopathy defined by an uncontrolled proliferation of cardiomyocytes." (PMID 33598462, 2021). "It has recently been shown that ALMS1 is an important molecule for cell cycle regulation in perinatal cardiomyocytes and that deficiency of the protein may lead to a mitogenic cardiomyopathy." (PMID 26104972, 2015). "Early-onset cardiomyopathy is likely related to earlier transcription termination of the ALMS1 gene." (PMID 35211159, 2022). "We first set out to assess whether our novel global Alms1 KO mouse model can recapitulate the infantile cardiomyopathy of AS." (PMID 38756069, 2024). "Therefore, we propose utilizing WES as the first diagnostic tool to establish an early diagnosis for neonatal cardiomyopathies, ALMS1 should be added to the cardiomyopathy gene panel." (PMID 34387706, 2021).
cardiomyopathy (continued). "This patient had a milder phenotype than other patients with convincing biallelic ALMS1 mutations, and also reported two siblings who were not available for study with cardiomyopathy, blindness, and deafness." (PMID 28717663, 2017). "In toto, although we detected early cardiac abnormalities in 23-week-old female global Alms1 KO mice, this study demonstrates that mice do not faithfully replicate the severe biphasic cardiomyopathy common in human AS." (PMID 38756069, 2024). "Although no anatomical defects or cardiomyopathy were seen in these mice after birth, 23-week-old female mice lacking ALMS1 showed evidence of heart stiffness and impaired pumping, but without all the severe signs of cardiomyopathy that are common in humans." (PMID 38756069, 2024). "Despite the prominence of cardiomyopathy in AS, and the high importance assigned to improving understanding of this by patients and families, such analysis has not been reported for any prior Alms1 KO model." (PMID 38756069, 2024).
type 2 diabetes (13 papers, 2014 to 2026). "First, in the family GBB23 with two siblings with biallelic BBS1 variants causing a clinical diagnosis of BBS, the proband also carries a third missense allele in ALMS1 (p.(His3880Tyr)), developed type 2 diabetes mellitus (T2DM)." (PMID 35835773, 2022). "Patients with Alström syndrome are more likely to develop childhood type 2 diabetes mellitus (T2DM) than patients with other syndromes, suggesting that ALMS1 may be of significance in the cell function and/or peripheral insulin signaling pathway." (PMID 36263163, 2022).
diabetes (12 papers, 2013 to 2025). "These disorders are characterized by early-onset obesity, insulin resistance, diabetes mellitus, retinodystrophy and other symptoms, but some features may also occur in heterozygous carriers of pathogenic or likely pathogenic variants in ALMS1 and BBS genes." (PMID 41312125, 2025). "Another ALMS mouse model, the fat aussie mouse with exon 8 Alms1 deletion, develops spontaneous diabetes with elevated fasting glucose and glucose intolerance, where even massive islet hyperplasia cannot produce enough insulin to match the demand." (PMID 35813631, 2022). "Islet function in these models, however, was not examined in isolation, independent of the whole-body metabolic defects, so it remained unclear whether Alms1-dependent ciliary changes and the diabetes phenotype seen in rodent models were related to intrinsic β-cell or islet dysfunction." (PMID 35813631, 2022).
Insulin resistance (12 papers, 2011 to 2026). Increased resistance towards insulin, that is, diminished effectiveness of insulin in reducing blood glucose levels. "Mutations in Alms1 are responsible for Alström syndrome, a rare genetic disorder leading to childhood obesity, severe insulin resistance, and multiple organ failure." (PMID 37373143, 2023). "In mice, a truncation mutant of Alms1 (foz/foz) leads to increased weight gain, insulin resistance, type 2 diabetes mellitus, and steatosis." (PMID 37373143, 2023).
Bardet-Biedl syndrome (9 papers, 2009 to 2025). A ciliopathy with multisystem involvement. "This study represents the first evaluation of the oral microbiome in patients with Alström and Bardet-Biedl syndromes and heterozygous carriers of causative variants in the ALMS1 and BBS genes." (PMID 41304128, 2025). "Alstrom syndrome is caused by mutations in a gene of unknown function (ALMS1) and it is characterized by several reminiscent phenotypes of Biedl-Bardet syndrome, including retinal degeneration, obesity and diabetes." (PMID 20108498, 2009).
Hyperinsulinemia (9 papers, 2011 to 2026). An increased concentration of insulin in the blood. "Global Alms1 KO males showed unaltered glycaemic excursion after oral glucose, but severe hyperinsulinemia, and MSC-KO mice showed a trend towards increased glucose excursion and insulinemia on oGTT." (PMID 38583571, 2024). "Consistent with hyperinsulinemia seen in ALMS patients, loss of Alms1 in β-cells of zebrafish also exhibited hyperinsulinemia and an impairment in glucose-stimulated insulin secretion (GSIS)." (PMID 35832432, 2022). "A gene trap insertion in Alms1 on the insulin sensitive C57BL6/Ei genetic background leads to early hyperinsulinemia and a progressive increase in body weight." (PMID 25299671, 2014). "Normoglycemic hyperinsulinemia was recapitulated in male Alms1 MSC-KO mice at 19 weeks." (PMID 38583571, 2024). "To elucidate a possible role of ALMS1 in the control of fat deposition, we analyzed the adipose tissue depots of Alms1GT/GT at 6 weeks of age, prior to weight gain and the onset of circulating hyperinsulinemia." (PMID 25299671, 2014).
dilated cardiomyopathy (8 papers, 2021 to 2025). Cardiomyopathy which is characterized by dilation and contractile dysfunction of the left and right ventricles. "These cases highlight the importance of genetic testing targeting the ALMS1 gene in the assessment of apparently isolated dilated cardiomyopathy." (PMID 39742192, 2024).
Retinal dystrophy (7 papers, 2017 to 2026). Retinal dystrophy is an abnormality of the retina associated with a hereditary process. "This further supports a previous report which demonstrated mutations in ALMS1 can cause non-syndromic retinal dystrophy." (PMID 30029497, 2018). "Pathogenic variants in the ALMS1 protein may affect the transport of retinal and other proteins along photoreceptor axons, and transport dysfunction leads to a retinal dystrophy phenotype, as well as affects multi-organ cilia function." (PMID 36162988, 2022).
metabolic syndrome (5 papers, 2017 to 2026). A cluster of metabolic risk factors for CARDIOVASCULAR DISEASES and TYPE 2 DIABETES MELLITUS. "At 24 weeks, global Alms1 KO mice were indeed strikingly hyperlipidemic, albeit with a different pattern to human dyslipidemia, which features elevated serum triglyceride and suppressed HDL cholesterol." (PMID 38583571, 2024). "Loss of Alms1 limited to MSC-derived cells including preadipocytes is sufficient to cause relative adipose failure on HFD, with secondary fatty liver and dyslipidemia despite intact hepatocyte Alms1 expression." (PMID 38583571, 2024). "Moreover, female Alms1 KO rats develop severe metabolic syndrome with hypertension, like males, demonstrating a lack of the typical female cardiovascular protection." (PMID 41691606, 2026).
cone-rod dystrophy (4 papers, 2016 to 2025). Inherited retinal dystrophies that belong to the group of pigmentary retinopathies. "We identified two compound heterozygous ALMS1 mutations in a Chinese quartet family shared between two siblings suffering cone-rod dystrophy and short stature." (PMID 28724398, 2017).
hearing loss (4 papers, 2010 to 2024). "An ALMS1 gene premature termination codon (p.Arg4052Glyfs*2) is produced by a homozygous frameshift deletion in exon 20 (c.12154_12166del), according to whole-exome sequencing of a 10-year-old Saudi girl who presented with diabetic ketoacidosis, hearing loss, and blindness." (PMID 38883102, 2024). "ALMS1 specifically localizes to the centrosome or basal body of cilia and other basal body proteins have likewise been associated with hearing loss but not vestibular dysfunction." (PMID 33793549, 2021).
Hyperglycemia (4 papers, 2014 to 2025). An increased concentration of glucose in the blood. "Male mice showed no hyperglycemia at 10 or 19 weeks, but at both time-points, global Alms1 KO mice were severely hyperinsulinemic, with insulin concentrations around 10-fold higher than controls." (PMID 38583571, 2024). "Female global Alms1 KO mice were hyperglycaemic at both timepoints, and MSC-KO mice only at 19 weeks, with plasma insulin concentrations markedly increased whenever hyperglycemia was observed." (PMID 38583571, 2024).
Hypertension (4 papers, 2019 to 2026). The presence of chronic increased pressure in the systemic arterial system. "Genetic studies have further associated Alms1 with hypertension in human populations." (PMID 41691606, 2026). "Alms1 knockout rats developed hypertension (a feature observed in 30% of AS patients), suggested to be due at least in part to NKCC2 accumulation at the apical cell surface and higher TAL NaCl transport." (PMID 30421101, 2019). "This is important because SNPs in ACTN4 are associated to hypertension in the general population and it is possible that ACTN4 is also involved in hypertension by modulating the ALMS1-NKCC2 interaction or acting independently on ALMS1 on NKCC2 to mediate its endocytosis." (PMID 39717823, 2024). "Alms1 KO rats are reported to be hypertensive, attributed to altered tubular trafficking of the Na+/K+/2Cl− (NKCC) co-transporter, and hypertension is observed in ∼30% of patients with AS." (PMID 38756069, 2024).
chronic kidney disease (3 papers, 2018 to 2025). Impairment of the renal function secondary to chronic kidney damage persisting for three or more months. "As previously reported, metabolites in N-acetyl amino acid and is associated with a region in gene ALMS1, which was found to be associated with chronic kidney disease." (PMID 39975339, 2025). "This region, mapped to ALMS1, is associated with chronic kidney disease, a disease that disproportionately burdens individuals of African descent." (PMID 37461045, 2023). "Several GWAS also reported variants in or near ALMS1 to be associated with chronic kidney disease." (PMID 29547645, 2018).
deafness (3 papers, 2017 to 2024). An inherited or acquired condition characterized by the complete loss of the ability to hear from one or both ears. "Neurogenic deafness and visual impairment are the most consistent symptoms of AS, and the function of the ALMS1 gene in auditory and visual maintenance has also been validated in some animal models." (PMID 39095761, 2024).
heart failure (3 papers, 2024 to 2025). Inability of the heart to pump blood at an adequate rate to meet tissue metabolic requirements. "There were no changes in the expression of genes typically associated with heart failure or fibrosis in male Alms1 KO mice." (PMID 38756069, 2024). "Collectively, these findings suggest that early recognition and standard heart-failure management can lead to functional stabilization and improved survival in infantile-onset cases, although no ALMS1-targeted therapy has yet been established." (PMID 41466426, 2025).
hypertrophic cardiomyopathy (3 papers, 2021 to 2024). A condition in which the myocardium is hypertrophied without an obvious cause. "Recently, hypertrophic cardiomyopathy (HCM) in Sphynx cats has been associated with a variant in the gene encoding Alström syndrome protein 1 (ALMS1)." (PMID 39335220, 2024). "A variation in the Alström syndrome protein 1 (ALMS1) gene was recently identified as a possible cause of hypertrophic cardiomyopathy (HCM) in Sphynx cats." (PMID 39335220, 2024). "This is the first report of a variant in the Alstrom syndrome protein 1 (ALMS1) gene in a domestic animal and the first report of an ALMS1 variant associated with the development of hypertrophic cardiomyopathy." (PMID 33639992, 2021). "We demonstrated that cats with hypertrophic cardiomyopathy and the variant in the ALMS1 gene had significantly more myocyte nuclear activity than the control cats." (PMID 33639992, 2021). "Here we describe the association of familial hypertrophic cardiomyopathy in Sphynx cats with a novel ALMS1 mutation." (PMID 33639992, 2021). "A G/C variant was identified in exon 12 (human exon 13) of the ALMS1 gene in affected cats and was positively associated with the presence of hypertrophic cardiomyopathy in the feline population (p < 0.0001)." (PMID 33639992, 2021). "Our findings suggest that variants in genes involved with other stages of cardiac development and cell regulation, like the ALMS1 gene, may deserve further consideration for association with familial hypertrophic cardiomyopathy." (PMID 33639992, 2021). "Our findings suggest that variants in genes involved with cardiac development and cell regulation, like the ALMS1 gene, may deserve further consideration for association with familial hypertrophic cardiomyopathy." (PMID 33639992, 2021). "The other nine (1–6 years of age; 4 females, 5 males) affected Sphynx cats did not have either the ALMS1 variants or the two known feline hypertrophic cardiomyopathy MYBPC3 mutations." (PMID 33639992, 2021). "Hypertrophic cardiomyopathy is not an identified consequence of ALMS1 variant in humans." (PMID 39335220, 2024). "It is possible that the affected Sphynx cats without the ALMS1 variant obtained a different causative variant from the general cat population since it has been estimated that approximately 15% of domestic cats suffer from hypertrophic cardiomyopathy." (PMID 33639992, 2021). "Not all Sphynx cats with hypertrophic cardiomyopathy evaluated here had the ALMS1 variants." (PMID 33639992, 2021).
hypogonadism (3 papers, 2011 to 2025). A disorder characterized by decreased function of the gonads. "To widen the understanding of hypogonadism in AS, we carried out testicular analysis in Alms1 S701X/S701X mutant mouse model (Mut) and compared it with littermate WT mice." (PMID 40512811, 2025). "Additionally, gonadal assessment and sperm characteristics were further explored in the Alms1 S701X mouse model to enhance the characterization of hypogonadism in AS." (PMID 40512811, 2025).
Leber congenital amaurosis (3 papers, 2015 to 2022). Leber congenital amaurosis (LCA) is a retinal dystrophy defined by blindness and responses to electrophysiological stimulation (Ganzfeld electroretinogram (ERG)) below threshold, associated with severe visual impairment within the first year of life. "Several recent studies have identified biallelic ALMS1 variants in patients with Leber congenital amaurosis (LCA) or LCA-like RD, as well as with early-onset severe cone-rod dystrophy (CORD), as RD was usually the first and only clinical symptom of AS appearing in infants or toddlers." (PMID 36685911, 2022).
liver fibrosis (3 papers, 2023 to 2026). "Pathogenic variants in IFT88, which are related to Bardet-Biedl Syndrome, can lead to liver fibrosis, while ALMS1 (linked to Alström Syndrome) and NEK8 (associated with Nephronophthisis) are involved in renal cysts and liver fibrosis." (PMID 40277920, 2025).
Nystagmus (3 papers, 2017 to 2024). Rhythmic, involuntary oscillations of one or both eyes related to abnormality in fixation, conjugate gaze, or vestibular mechanisms. "We identified homozygosity for a novel ALMS1 1-bp deletion (c.1092del; p.Asp365Ilefs*11) in two brothers initially addressed for profound visual deficiency with nystagmus near birth." (PMID 38892339, 2024).
restrictive cardiomyopathy (3 papers, 2011 to 2025). A type of heart disorder referring to the inability of the ventricles to fill with blood because the myocardium (heart muscle) stiffens and looses its flexibility. "Nevertheless, our findings, collectively, do indicate mild combined systolic and diastolic dysfunction that is reminiscent of the restrictive cardiomyopathy of AS, at least in adult female Alms1 KO mice." (PMID 38756069, 2024).
retinal degeneration (3 papers, 2012 to 2021). Degeneration of the retina. "However, Xu and colleagues have reported homozygous ALMS1 null mutation in six LCA cases with early-onset retinal degeneration, visual acuity from light perception to no light, high hyperopia, roving eye movement, oculo-digital sign, undetectable ERG and tapetal fundus." (PMID 33957996, 2021).
retinal diseases (3 papers, 2020 to 2024). "Since no second candidate variant was identified in ABCA4 or ALMS1, both of which have been associated with recessive forms of retinal diseases, these variants alone could not explain the phenotype in the index patient." (PMID 39766771, 2024).